LCAT (lecithin-cholesterol acyltransferase)
Diseases named in the same sentence as LCAT in open-access papers (continued):
Sharing a sentence is not in itself a finding about the gene and the disease.
dyslipidemia (23 papers, 2009 to 2025). "LCAT deficiency in hamsters leads to dyslipidemia, characterized by hypertriglyceridemia, reduced HDL-C levels, and elevated TG levels, which is similar to the pathological condition of human LCAT deficiency." (PMID 41516253, 2025). "Patients with chronic kidney disease face an elevated risk of developing dyslipidemia because of reduced activities of lipoprotein lipase and lecithin cholesterol acyltransferase, along with lower hepatic lipase levels." (PMID 40725745, 2025). "The LCAT gene polymorphism has been proven to increase the risk of dyslipidemia and coronary atherosclerotic heart disease by decreasing the plasma high density lipoprotein cholesterol (HDL-C) levels in humans." (PMID 36456907, 2022). "Exploration of gene–gene and gene–environmental interactions demonstrated that APOA1, ABCA1, and LCAT polymorphisms significantly contribute to dyslipidemia development." (PMID 33805921, 2021). "Our findings suggested that the interaction among APOA1, ABCA1, LCAT conferred the genetic susceptibility to dyslipidemia in Xinjiang Rural Area." (PMID 29758034, 2018). "In the current study, we explored associations of APOA1, ABCA1, and LCAT genes with dyslipidemia and focused on gene polymorphisms involved in the RCT system." (PMID 29758034, 2018). "Human genetic data from several independent genome-wide studies confirm an association between SNPs in the LCAT gene and dyslipidemia (14, –, 16)." (PMID 26644477, 2016). "Eventually, the approaches presented in this study may lead to the development of more advanced apolipoprotein mimetic peptides that could be used in the treatment of different metabolic disorders, such as dyslipidemia and LCAT deficiencies." (PMID 29438987, 2018). "Moreover, an HFD exacerbates dyslipidemia and accelerates the progression of atherosclerotic lesions in LCAT-deficient hamsters, making it a valuable model for studies on lipid metabolism disorders and related cardiovascular diseases, especially atherosclerosis." (PMID 41516253, 2025). "Although the relationship between metabolic syndrome, obesity, and CRC has been widely proven, a challenge for future researchers is to examine the significance of the most prevalent CETP and LCAT polymorphisms for the onset of CRC." (PMID 33805921, 2021). "The influence of this SNP identified at position 97 of the mutant LCAT on plasma HDL cholesterol concentration is evidenced by the findings that hypoalphalipoproteinemia is one of the highest prevalent form of dyslipidemia present in this study." (PMID 33173066, 2020). "27C3 and other agonistic human anti-human LCAT monoclonal antibodies described herein hold potential for therapeutic development for the treatment of dyslipidemia and cardiovascular disease." (PMID 26644477, 2016). "Interestingly, CER-001 appears to have a therapeutic target in LCAT deficiency, as shown in LCAT-/- mice treated with CER-001, there was improvement in dyslipidemia and renal function." (PMID 36651718, 2023). "Based on previous observations, we hypothesized that dyslipidemia is jointly caused by the APOA1, ABCA1, and LCAT genes and their interactions with environmental factors." (PMID 29758034, 2018). "Therefore, to explore gene-gene and gene-environment interactions underlying dyslipidemia, we investigated five (rs670, rs1800976, rs4149313, rs2292318, rs1109166) single nucleotide polymorphisms (SNPs) located in APOA1, ABCA1, and LCAT based on a model RCT pathway." (PMID 29758034, 2018). "Several factors, including decreased activities of lipoprotein lipase and lecithin cholesterol acyltransferase (LCAT) and decreased hepatic lipase levels, promote dyslipidemia development in chronic kidney disease patients." (PMID 33917145, 2021). "In fact, low LCAT activity has been described in patients with type 2 diabetes and metabolic syndrome compared to patients without metabolic syndrome." (PMID 37237999, 2023).
dyslipidemia (continued). "Serum LCAT activity is elevated in patients with serum high triglyceride and low high-density lipoprotein-cholesterol (HDL-C) concentrations, both of which are related to metabolic syndrome and subsequent diabetes mellitus, referred to as lipotoxicity." (PMID 30055622, 2018). "Thus, dyslipidemia is influenced by APOA1, ABCA1, LCAT, environmental factors, and their interactions." (PMID 29758034, 2018). "In that study, we also observed that serum LCAT activity was highly correlated with increased waist circumference, increased serum TG concentration, and decreased serum HDL-C concentration, all of which are components of metabolic syndrome and are related to insulin resistance." (PMID 30055622, 2018). "The in vivo results of the present study showed that Tx patients with and without statin therapy had moderate dyslipidemia, dyslipoproteinemia, and atherogenic lipid and lipoprotein ratios, decreased LCAT mass, and slightly increased hsCRP, but no CETP activity." (PMID 23479335, 2013).
chronic kidney disease (16 papers, 2012 to 2025). Impairment of the renal function secondary to chronic kidney damage persisting for three or more months. "Chronic kidney disease (CKD) is often associated with decreased activity of lecithin-cholesterol acyltransferase (LCAT), an enzyme essential for HDL maturation." (PMID 39154733, 2024). "The proband’s severe alteration of lipid profile, HDL subclass distribution and cholesterol esterification in plasma was the result of the LCAT P406L variant and of the concomitant chronic renal insufficiency." (PMID 22658148, 2012). "Down-regulation of hepatic lecithin-cholesterol acyltransferase (LCAT) expression occurs in chronic renal failure." (PMID 39154733, 2024). "Patients with chronic kidney disease have downregulation of the expression of hepatic apolipoprotein A-I and lecithin cholesterol acyltransferase, which results in impaired high-density lipoprotein-mediated cholesterol uptake from vascular tissue." (PMID 35565954, 2022). "Studies have shown that lower plasma apoA-I and plasma lecithin-cholesterol acyltransferase activity are present in subjects with chronic renal failure and lead to impaired HDL-mediated reverse cholesterol transport." (PMID 33093546, 2020). "This may be related to impaired LCAT-dependent conversion, as liver LCAT gene expression is downregulated in end-stage renal disease." (PMID 40004147, 2025). "Moreover, in patients with chronic kidney disease, the activity of lecithin–cholesterol acyltransferase (LCAT), which is responsible for the esterification of free cholesterol in HDL, is compromised." (PMID 31752189, 2019). "On one side, chronic kidney disease (CKD) affects plasma HDL levels, HDL structure and subclass distribution, and HDL functionality; on the other side, inherited HDL disorders can lead to kidney dysfunction, as in LCAT deficiency." (PMID 33807271, 2021). "HDL-c and LCAT do not correlate in the present study, differently from what was observed in end stage renal disease patients but in agreement with the absence of correlation observed in the general population." (PMID 32708515, 2020). "Although no studies to date have investigated the role of LCAT in pulmonary diseases, emerging evidence from research on chronic kidney disease (CKD) offered preliminary insights into its potential systemic regulatory functions." (PMID 40927188, 2025). "In end-stage renal disease (ESRD) patients, non-enzymatic glycation of apoA-I results in a diminished activation of LCAT leading in consequence to higher apoA-I clearance from circulation and in hampered anti-inflammatory and antioxidant properties of HDL." (PMID 31752189, 2019).
coronary artery disease (15 papers, 2012 to 2024). "However, we have previously reported that increased serum LCAT activity measured as serum cholesterol esterification rates were associated with future risk of coronary heart disease and sudden death in a general population." (PMID 30055622, 2018). "Another study in subjects with ischemic heart disease revealed a strong association of ischemic heart disease with low plasma LCAT activity, suggesting that LCAT activity might be useful as a biomarker for identifying patients at risk for CVD." (PMID 26644477, 2016). "There are few reports yet of large-scale prospective cohort studies investigating LCAT activity in relation to the prognosis of coronary artery disease." (PMID 30518338, 2018). "Therefore, increased serum LCAT activities may play a pivotal role in the development of both diabetes mellitus and coronary heart disease among various lipid markers." (PMID 30055622, 2018). "Increased LCAT concentration might therefore exert atheroprotective functions in coronary artery disease (CAD) and atherosclerotic cardiovascular disease patients." (PMID 36588724, 2022). "Interestingly, studies have identified a negative association between LCAT mass concentration and intravascular ultrasonography-assessed plaque volume in patients with coronary artery disease (CAD)." (PMID 39001966, 2024).
Insulin resistance (14 papers, 2015 to 2025). Increased resistance towards insulin, that is, diminished effectiveness of insulin in reducing blood glucose levels. "Taken together, hypertriglyceridemia may cause insulin resistance through LCAT dependent pathways." (PMID 30055622, 2018). "In age- and sex-adjusted partial linear regression analysis, LCAT activity is positively related to various obesity measures and homeostasis model assessment-insulin resistance (HOMA-IR)." (PMID 39204178, 2024). "Contrary to the present findings in dairy cows, plasma LCAT activity was shown to be increased in human patients with insulin resistance." (PMID 26034989, 2015). "Therefore, MASLD inferred from an FLI ≥ 60 confers higher plasma LCAT and, to a lesser extent, phospholipid transfer protein activity, even when accounting for T2DM, MetS, central obesity, and insulin resistance." (PMID 39204178, 2024). "Defective ABCA1 mediating the efflux of cellular free cholesterol, defective LCAT activity, or increased selective delivery of HDL cholesteryl ester to hepatocytes may be involved in the low HDL levels present with severe insulin resistance." (PMID 30049949, 2018). "However, during the deliberately induced NEB around 100 DIM, plasma LCAT activity showed no change in RES cows and stayed on the same high level as in CON cows without any insulin resistance." (PMID 26034989, 2015).
liver disease (14 papers, 2010 to 2025). "The histopathological similarities between hepatic glomerulosclerosis and LCAT deficiency suggest a potential link between liver disease and lipid deposition in the kidneys." (PMID 39114211, 2024). "In the present study the increase in plasma lysolipids of dogs with severe liver disease could have been caused by a possible increase in LCAT activity, with concomitant elevation of inflammatory compounds." (PMID 30551591, 2018). "Consistent with the previous finding that LCAT is less active in patients with liver diseases, our study demonstrates that LCAT is underexpressed in HCC." (PMID 36330335, 2022). "This is somewhat surprising considering that LCAT activity was reported to be substantially decreased in patients with liver disease." (PMID 33673728, 2021). "Lecithin-cholesterol acyltransferase (LCAT) is produced by the liver and secreted into the circulation, and patients with liver disease show reduced LCAT activity." (PMID 34925311, 2021). "LCAT is related to fatty metabolism in males, and its activity is reduced in patients with liver disease." (PMID 34034705, 2021). "LCAT is produced by the liver and secreted into the circulation and its activity can be attenuated in patients with liver disease." (PMID 31695766, 2019). "Although reduced LCAT activity is common in a variety of liver diseases, the current report is, to the best of our knowledge, the first to identify increased CETP and PLTP activities as being associated with chronic liver impairment." (PMID 20470383, 2010). "In liver diseases, the underexpression of LCAT may result in restricted cellular cholesterol efflux, which increases the risk for fatty liver disease and liver cancer." (PMID 36330335, 2022). "LCAT activity itself is a sensitive parameter for the severity of the liver disease." (PMID 27840599, 2016). "For example, patients with severe liver disease have lower circulating LCAT, cholesteryl ester transfer protein (CETP) and higher HL than healthy subjects, raising the possibility that defective lipoprotein remodeling and catabolism may account for the appearance of LP-Z." (PMID 32927635, 2020). "Previous studies support the hypothesis that LCAT, CETP, HL, apoA-I and apoA-IV are reduced in patients with liver disease and cirrhosis." (PMID 32927635, 2020). "Additionally, the role of LP-Z as opposed to LP-X, an abnormal discoidal lipoprotein with increased free cholesterol content, which can be produced as a consequence of liver disease-induced impaired LCAT activity, has not been established." (PMID 35268313, 2022).
hyperlipidemia (13 papers, 2014 to 2025). "NKT attenuates lipid peroxidation, enhances antioxidant defense mechanisms, and favorably modulates HMG-CoA reductase and LCAT, thereby preventing hyperlipidemia, altered lipoproteins, and hypertrophy in a rat model of MI induced by ISO." (PMID 33266249, 2020). "BPF enhances LCAT, suggesting that hyperlipidemia is able to affect the physiological function of these LTPs." (PMID 31101130, 2019). "It was revealed that the mRNA expression of LCAT and SR-BI was decreased in the hyperlipidemia model group, compared with NCD group." (PMID 24829618, 2014). "Additionally, 6-gingerol prevents HFD-induced hyperlipidemia by modulating the expression of enzymes critical to cholesterol metabolism, including lecithin-cholesterol acyltransferase (LCAT) and LPL, as well as inflammatory markers such as TNF-α and IL-6." (PMID 40733199, 2025). "Several studies have suggested that LCAT expression and activity may be downregulated in specific hyperlipidemia symptoms." (PMID 37687178, 2023). "NKT treatment appears to regulate the synthesis of cholesterol by inhibiting the activity of HMG-CoA-R and by enhancing the HDL cholesterol turnover through increasing the activity of LCAT in ISO-triggered hyperlipidemia in rats, which is suggestive of the antihyperlipidemic property of NKT." (PMID 33266249, 2020). "The expression of LCAT was decreased in the HFD-induced hyperlipidemia model." (PMID 32581811, 2020). "The present study demonstrated a significant upregulation in several apolipoproteins, including APOC1, APOB, APOC4 and APOL1, but also in LCAT, suggesting a dysregulation in lipoprotein metabolism that could be partially related to the hyperlipidemia in IMN patients." (PMID 37511514, 2023). "SSTF was administrated at oral dosages of 25 mg, 50 mg, and 100 mg/kg/day in hyperlipidemia rats for 20 days, indicating that SSTF significantly reduced the serum TC, TG, and LDL-c levels and increased HDL-c and the activity of lecithin cholesterol acyltransferase (LCAT)." (PMID 24688589, 2014).
diabetes (12 papers, 2016 to 2026). "Data on LCAT activity in diabetes and MetS are scarce, making it difficult to understand the role of LCAT in the loss of ability of HDLs to induce NO production." (PMID 36837872, 2023). "Increased serum LCAT activities, measured as the serum cholesterol esterification rates, are associated with the future risk of diabetes mellitus in the general population." (PMID 30055622, 2018). "Among these, serum LCAT activities were significantly associated with future risk of diabetes mellitus." (PMID 30055622, 2018). "After adjustment for HbA1c, total cholesterol, triglyceride, HDL-C, phospholipid, and free fatty acid levels, the RR of LCAT activity for future risk of diabetes mellitus remained significant (RR, 4.93; 95% CI,1.32–18.41; P = 0.018)." (PMID 30055622, 2018). "Among these, BMI, increased TG, decreased HDL-C, and increased LCAT activity were associated with the risk of diabetes mellitus with relatively higher RRs than increased blood pressure in this population." (PMID 30055622, 2018). "Here, we examined the relationship between baseline LCAT activity, measured as serum cholesterol esterification rate, and future risk of diabetes mellitus in a general Japanese population." (PMID 30055622, 2018). "Taken together, we hypothesized that increased serum LCAT activity is predictive of future risk of diabetes mellitus." (PMID 30055622, 2018). "We hypothesized that increased serum LCAT activity could predict future risk of diabetes mellitus in a general Japanese population." (PMID 30055622, 2018). "However, in the analysis performed on men and women separately, we found a significant association between baseline LCAT activity and the future risk of diabetes mellitus only in men (RR 9.15; 95% CI, 1.02–81.95; P = 0.048 for men and RR, 2.67; 95% CI, 0.47–15.41; P = 0.27 for women)." (PMID 30055622, 2018). "As the disease progresses to diabetes, hepatic steatosis significantly worsens, accompanied by elevation of serum and urine LCAT." (PMID 41774528, 2026). "LCAT activity measured in the blood of diabetes patients before and after insulin treatment confirmed that glucose on its own cannot activate LCAT23." (PMID 39478139, 2024). "Data on LCAT are scare, showing an elevation in only two studies, making it difficult to understand the precise role of LCAT in the production of HDL-lysoPCs in diabetes and MetS." (PMID 36837872, 2023). "Model 3: adjusted for age; sex; diabetes status; use of metformin, sulfonylurea and antihypertensive medication; and LCAT activity (A) or CETP mass (B)." (PMID 30744100, 2019). "After adjustment for HbA1c levels, we found significant risk factors for diabetes mellitus including BMI, waist circumference, waist to hip ratio, systolic blood pressure, IRI, HDL-C, TG, and LCAT activity." (PMID 30055622, 2018). "In this analysis, we found a significant association between LCAT activity and risk of diabetes mellitus in men but not in women." (PMID 30055622, 2018). "Our study indicates that among various lipid markers, increased serum LCAT activity may play a pivotal role in the development of diabetes mellitus in the general population." (PMID 30055622, 2018). "Of note, the association of LCAT activity with betaine was no longer significant after adjustment for age, sex, diabetes status, BMI and lipoprotein variables or apolipoproteins (models 1 and 2)." (PMID 27581838, 2016). "However, others found LCAT activity rather decreased or unchanged in diabetes." (PMID 36979432, 2023). "When we performed a multivariable analysis including BMI as a covariate in addition to lipids and HbA1c levels, we could not find any significant associations between LCAT activity and risk of diabetes mellitus in this analysis (data not shown)." (PMID 30055622, 2018). "Therefore, increased LCAT activity was significantly associated with the risk of diabetes mellitus independent of other lipid markers." (PMID 30055622, 2018).